CXCR2P1 (C-X-C motif chemokine receptor 2 pseudogene 1)
Synonyms: formerly IL8RBP; CXCR2P
Gene: Transcribed unprocessed pseudogene on chromosome 2 (218,060,339 to 218,061,412, reverse strand). Ensembl gene ENSG00000229754.
Diseases named in the same sentence as CXCR2P1 in open-access papers:
CXCR2P1 is named in the same sentence as 13 diseases in open-access papers, as found by Europe PMC text mining. Sharing a sentence is not in itself a finding about the gene and the disease. The quoted sentences say what the papers report.
gastric cancer (2 papers, 2025). A primary or metastatic malignant neoplasm involving the stomach. "WGCNA identified CXCR2P1 as a hub gene significantly associated with immune response to PD-1 inhibitors in gastric cancer." (PMID 40176817, 2025). "This study explored the role of CXCR2P1 in the tumor immune response in detail, which provided a new target and idea for the immunotherapy of gastric cancer." (PMID 40176817, 2025). "In this study, we compared expression levels of CXCR2P1 in different groups from different public databases, validated the potential of CXCR2P1 as a predictor of prognosis in gastric cancer patients receiving PD-1 inhibitors." (PMID 40176817, 2025). "In gastric cancer tissues, the expression of CXCR2P1 is significantly elevated compared with normal gastric mucosa, and patients with high CXCR2P1 expression exhibit better prognosis and improved responses to PD-1 inhibitor." (PMID 40176817, 2025). "In four GEO datasets, expression of CXCR2P1 was higher in gastric cancer tissue than which in normal tissue (p < 0.001)." (PMID 40176817, 2025). "Comprehensively, our findings suggest that high CXCR2P1 expression may reduce hsa-miR-215-5p levels in tumor tissues through the lncRNA-microRNA regulatory axis, potentially improving the prognosis of gastric cancer patients." (PMID 40176817, 2025). "Finally, the signaling pathways involved in CXCR2P1 in gastric cancer cells were analyzed by differentially expressed genes analysis, enrichment analysis and co-expression analysis." (PMID 40176817, 2025).
sarcoma (2 papers, 2021 to 2022). A usually aggressive malignant neoplasm of the soft tissue or bone. "One bioinformatic analysis reported that the overexpression of the lncRNAs ADAM6, C5orf58, CXCR2P1, FCGR2C, HCP5, HLA-H, NAPSB, NCF1B, and NCF1C reduced the sensitivity of sarcoma to ICIs." (PMID 36326232, 2022). "The expression of nine ICLs, ADAM6, C5orf58, CXCR2P1, FCGR2C, HCP5, HLA-H, NAPSB, NCF1B and NCF1C, was further investigated in different cancer types, including sarcoma." (PMID 34178688, 2021).
bladder cancer (1 paper, 2022). "Several lncRNAs such as NCF1C, NCF1B, CXCR2P1, LINC02446, and AC0048473.1 have a high number of target genes that are associated with immune function, indicating that these lncRNAs are functionally related to immune activation in bladder cancer." (PMID 36091015, 2022).
lung carcinoma (1 paper, 2025). "Meanwhile, in the only two databases containing both results of response to PD-1 inhibitor and survival information (lung cancer and metastatic urothelial carcinoma), CXCR2P1 showed excellent prognostic value." (PMID 40176817, 2025). "Through Kaplan-Meier curves, we found CXCR2P1-high group had prolonged OS in patients with metastatic urothelial carcinoma (p < 0.0001) and prolonged PFS in patients with lung cancer (p = 0.013) than those in CXCR2P1-low group." (PMID 40176817, 2025).
metastatic melanoma (1 paper, 2020). A melanoma that has spread from its primary site to another anatomic site. "Survival and multivariate Cox regression analyses revealed four vital genes, namely, POU2AF1, ITGAL, CXCR2P1, and MZB1, that affect the prognosis of patients with metastatic melanoma." (PMID 33336008, 2020).
neuroblastoma (1 paper, 2022). Neuroblastoma (NB) is the most common solid, extracranial childhood tumor. "Using SVR‐NB, 35 lncRNAs have been identified, showing that 4 lncRNAs (LOC729770, CXCR2P1, LOC387720, and DUX4L3) may affect the overall survival of neuroblastoma patients." (PMID 35592755, 2022).
cancer (5 papers, 2019 to 2025). A tumor composed of atypical neoplastic, often pleomorphic cells that invade other tissues. "GSEA by c2wikipathway showed that CXCR2P1 was significantly enriched in Cancer Immunotherapy By PD-1 Blockade (p = 2.676 x 10-4)." (PMID 40176817, 2025). "As early as 2019, Choy found CXCR2P1 may have the ability to affect the response of tumor to immunotherapy through a pan-cancer machine-learning analysis." (PMID 40176817, 2025). "Two other stage-IV specific genes, namely the downregulated CXCR2P1, which is a C-X-C motif chemokine receptor 2 pseudogene 1, and LOC25845, are minimally documented in the literature in the context of HCC, other cancers or any other condition." (PMID 31277598, 2019). "Among these, CXCR2P1 has been speculated to be related to immune checkpoints PD-1, PD-L1, and CTLA4, which are crucial for successful cancer immunotherapy that contribute to the immune response, but there is still a lack of direct evidence." (PMID 36097539, 2022).
tumor (1 paper, 2025). "At the cellular level, CXCR2P1 is associated with inflammatory activation and enhanced antigen presentation in tumor tissues." (PMID 40176817, 2025). "ESTIMATE and CIBERSORT algorithm were used to evaluate the reshaping effect of CXCR2P1 to immune microenvironment of tumor." (PMID 40176817, 2025). "At the molecular level, CXCR2P1 upregulates PD-L1 expression in tumor tissues and activates key signaling pathways involved in PD-1 regulation." (PMID 40176817, 2025). "This research analyzed the cell biological role of CXCR2P1 firstly, explored the effect of CXCR2P1 on the tumor immune microenvironment, and provided new insights and references for the development of targeted therapies." (PMID 40176817, 2025). "At the molecular level, CXCR2P1 can activate immune-related signaling pathways and significantly increase the expression of PD-L1 in tumor tissues." (PMID 40176817, 2025). "In this study, we observed a significant positive correlation between the expression of CXCR2P1 and PD-L1 in tumor tissues." (PMID 40176817, 2025). "CXCR2P1 plays a vital role in reshaping the tumor immune microenvironment by promoting greater immune cell infiltration and significantly increasing the proportions of M1 macrophages, CD4+ T cells, and follicular helper T cells." (PMID 40176817, 2025). "GSEA and co-expression analysis revealed that tumor tissues with high CXCR2P1 expression exhibited significant activation of the PD-1 signaling pathway, IFN signaling pathway, Toll-like receptor signaling pathway, and JAK-STAT signaling pathway." (PMID 40176817, 2025). "Through comprehensive analysis, we explored the potential of CXCR2P1 as a prognostic predictor and its role in tumor immune response." (PMID 40176817, 2025). "By enhancing antigen presentation, CXCR2P1 may indirectly upregulates PD-L1 expression in tumor tissues by promoting immune cell infiltration." (PMID 40176817, 2025). "Results showed that in tumor tissue, with the increasing expression of CXCR2P1, Toll Like Receptor Signaling Pathway(p = 5.684 x 10-7), Modulators of TCR Signaling And T Cell Activation(p = 1.685 x 10-3) and Interferon Alpha Signaling Pathway (p = 1.0 x 10-10) were significantly activated." (PMID 40176817, 2025). "GSEA by c2wikipathway database showed that CXCR2P1 was significantly enriched to Interactions Between Immune Cells And MicroRNAs In Tumor Microenvironment (2.402 x 10-3), which indicated that CXCR2P1 might regulate the expression of PD-L1 through microRNAs." (PMID 40176817, 2025). "Our results indicated that CXCR2P1 may indirectly up-regulate the expression of PD-L1 in tumor cells by increasing immune infiltration and enhancing the activation of T cells in the tumor tissue." (PMID 40176817, 2025). "The expression of CXCR2P1 can influence the tumor immune microenvironment significantly." (PMID 40176817, 2025). "From GSEA analysis, we found CXCR2P1 was enriched into microRNAs in tumor microenvironments, which indicated that CXCR2P1 might affect the cell phenotype through microRNAs." (PMID 40176817, 2025). "The role of CXCR2P1 in tumor development and its effect on tumor immune microenvironment still remains unknown." (PMID 40176817, 2025). "Meanwhile, we analyzed the correlation between CXCR2P1 and tumor microenvironment." (PMID 40176817, 2025). "In tumor immune microenvironment, CXCR2P1 can promote inflammation, enhance antigen presentation and activate the PD-1/PD-L1-related signaling pathway, which might be achieved by CXCR2P1-MIR215 axis." (PMID 40176817, 2025). "Hence, tumors with high expression of CXCR2P1 may have more active tumor immune microenvironment, which laid a foundation for good immune response." (PMID 40176817, 2025). "Our research found that the expression of CXCR2P1 was positively correlated with the number of M1 macrophages and activated CD4+ T cells in the tumor microenvironment." (PMID 40176817, 2025).
tumor (continued). "Our study showed that the expression of CXCR2P1 was higher in responders and tumor tissue than those in non-responders and normal tissue." (PMID 40176817, 2025). "In our study, tumor tissues with high CXCR2P1 expression exhibited significantly higher proportions of activated CD4+ T cells and TFH cells compared to low CXCR2P1 expression tumor, suggesting that the tumor tissues with high CXCR2P1 expression may have higher immunogenicity." (PMID 40176817, 2025).
CXCR2P1 also shares sentences with these, for which no sentence is quoted: head and neck squamous cell carcinoma (1 paper); hepatocellular carcinoma (1); melanoma (1); metastatic tumors (1); serous ovarian cancer (1).